IL21 (interleukin 21)
Description:
Cytokine with immunoregulatory activity. May promote the transition between innate and adaptive immunity. Induces the production of IgG(1) and IgG(3) in B-cells (By similarity). Implicated in the generation and maintenance of T follicular helper (Tfh) cells and the formation of germinal-centers. Together with IL6, control the early generation of Tfh cells and are critical for an effective antibody response to acute viral infection (By similarity). May play a role in proliferation and maturation of natural killer (NK) cells in synergy with IL15. May regulate proliferation of mature B- and T-cells in response to activating stimuli. In synergy with IL15 and IL18 stimulates interferon gamma production in T-cells and NK cells. During T-cell mediated immune response may inhibit dendritic cells (DC) activation and maturation (By similarity).
Synonyms: IL-21; Za11; CVID11
Tractability: Small molecule: a structure with a bound ligand is known. Antibody: UniProt places it where antibodies can reach, with high confidence; its Gene Ontology location is reachable by antibodies, with high confidence; UniProt predicts a signal peptide or a membrane-spanning region. Other modalities: a drug acting on it is in phase 2 or 3 trials.
Target class: Secreted protein
Gene: Protein-coding gene on chromosome 4 (122,610,108 to 122,621,066, reverse strand). Ensembl gene ENSG00000138684.
Subcellular location: Secreted
Pathways (Reactome):
Immune System: Interleukin-21 signaling
Gene Ontology:
Molecular function: interleukin-2 receptor binding; protein binding; cytokine receptor binding
Biological process: cell maturation; positive regulation of B cell proliferation; positive regulation of cell population proliferation; positive regulation of cytokine production; positive regulation of interleukin-17 production; positive regulation of natural killer cell mediated cytotoxicity; positive regulation of T cell proliferation; positive regulation of tyrosine phosphorylation of STAT protein; tyrosine phosphorylation of STAT protein; cell surface receptor signaling pathway via JAK-STAT; cellular response to virus; defense response to virus; germinal center B cell differentiation; immunoglobulin mediated immune response; natural killer cell activation; positive regulation of immunoglobulin production; positive regulation of inflammatory response; positive regulation of tissue remodeling; positive regulation of type II interferon production; signal transduction; T follicular helper cell differentiation; cell development; immune response; positive regulation of lymphocyte activation; response to virus
Cellular component: plasma membrane; extracellular region
Genetic constraint (gnomAD): Loss-of-function variants: 3 observed, 17.23 expected, observed/expected ratio (o/e) 0.17, 90% interval 0.078 to 0.45. The synonymous counts are far from expectation, so gnomAD's model fits this gene poorly and the ratio says little. Missense variants: 120 observed, 179.96 expected, observed/expected ratio (o/e) 0.67, 90% interval 0.57 to 0.78. Synonymous variants: 32 observed, 58.76 expected, observed/expected ratio (o/e) 0.54, 90% interval 0.41 to 0.73.
Gene-disease validity (ClinGen):
ClinGen rates the evidence that IL21 causes each of these diseases.
IL21-related infantile inflammatory bowel disease (autosomal recessive): Limited.
Homologues: Orthologues: chimpanzee IL21 (100% identical), macaque IL21 (96% identical), pig IL21 (76% identical), dog IL21 (73% identical), guinea pig IL21 (70% identical), rabbit IL21 (65% identical), mouse Il21 (57% identical), rat Il21 (51% identical), tropical clawed frog il21 (25% identical).
Diseases named in the same sentence as IL21 in open-access papers:
IL21 is named in the same sentence as 385 diseases in open-access papers, as found by Europe PMC text mining. Sharing a sentence is not in itself a finding about the gene and the disease. The quoted sentences say what the papers report.
autoimmune disease (163 papers, 2008 to 2025). A disorder resulting from loss of function or tissue destruction of an organ or multiple organs, arising from humoral or cellular immune responses of the individual to their own tissue constituents. "IL21 encodes IL-21, which is a signature cytokine of Tfh-like cells and plays a crucial role in ICIs-based immunotherapy and autoimmune diseases." (PMID 40519906, 2025). "Genome-wide association studies established a possible role of the IL21/IL2 region in the human autoimmune diseases RA, SLE, type 1 DM, and SS." (PMID 39746095, 2025). "Th17 cells are involved in the control of bacterial and fungal infections, are associated with autoimmune diseases, and induce the production of proinflammatory cytokines such as IL-6, IL-21, TGF-β, and particularly IL-23." (PMID 41552147, 2025). "Conversely, the mRNA BNT162b2 vaccine is thought to indirectly promote the production of IL-4, IL-17, and IL-21 cytokines, which have associations with autoimmune disorders." (PMID 39203983, 2024). "One SNP, i.e., rs6822844, is an intronic variant in the KIAA1109/Tenr/IL2/IL21 block and has been identified as a risk factor in several autoimmune diseases, including celiac disease, rheumatoid arthritis and type 1 diabetes." (PMID 38232165, 2024). "Due to the involvement of IL-21 in autoimmune diseases, it is possible that these polymorphisms are associated with RA development and IL-21 levels." (PMID 37107636, 2023). "The increase in IL-21 levels in autoimmune diseases, and its association with RA clinical manifestations, such as the relationship with autoantibodies, suggests a regulation mechanism via IL-21/IL-21R." (PMID 37107636, 2023). "IL-21/IL21R polymorphisms have also been reported to be associated with risk for autoimmune diseases such as multiple sclerosis, autoimmune thyroid diseases, SLE, and RA." (PMID 37107636, 2023). "Interleukin-21 (IL-21) plays a critical role in generating immunological memory by promoting the germinal center reaction, yet clinical use of IL-21 remains challenging because of its pleiotropy and association with autoimmune disease." (PMID 37339051, 2023). "Previous investigations reported the association of diverse IL-21 and IL-21R polymorphisms with autoimmune disorders, such as systemic lupus erythematosus (SLE), multiple sclerosis, autoimmune thyroid diseases, and RA, in different populations." (PMID 37107636, 2023). "A major challenge to the use of IL-21 clinically is its association with the induction of autoimmune disease." (PMID 37339051, 2023). "IL-21 is a multifunctional cytokine linked with the pathophysiology of several autoimmune diseases, including type 1 diabetes." (PMID 37415982, 2023). "Lymphocytes T and B are activated following BNT162b2 administration, and IL-2, IL-4, IL-17, and IL-21 are associated with autoimmune diseases, especially in genetically susceptible individuals." (PMID 37238357, 2023). "The pathogenic role of the interleukin 21 (IL-21) in different autoimmune diseases, such as multiple sclerosis (MS), has been extensively studied." (PMID 35902536, 2022). "Whereas IL-21 provides signals to promote lymphocyte differentiation and has been implicated in the development of several autoimmune diseases, IL-21 can paradoxically elicit immunosuppressive responses through induction of IL-10 secretion by T cells." (PMID 36466865, 2022). "The results indicate the underlying mechanisms of how IL-4 and IL-21 differentially promote survival of hyperactivated B cells and provide hints to treat autoimmune diseases." (PMID 35911775, 2022). "Several single-nucleotide polymorphisms (SNPs) situated in IL2/IL21 region including: rs13151961, rs13119723, rs6840978, and rs6822844 have proven to be significantly associated with many autoimmune disorders, such as RA." (PMID 31366568, 2019).
autoimmune disease (continued). "Recently, it was reported that naïve Th21 cells, which are implicated in autoimmune disease, do also express a combination of cytokines (IL-21 and IFNγ) typically associated with different Th cell lineages." (PMID 29973931, 2018). "IL-23R deletion reduces Th17 cells and ameliorates autoimmune diseases in Act1−/− mice, implicating the importance of hyper Th17 cells (with increased STAT3 activation and IL-21 expression) for the autoimmune diseases associated with Act1 deficiency." (PMID 30013031, 2018). "Th17 cells differentiate in response to IL-1β, IL-6, IL-23, and TNF-α; secrete IL-17A, IL-17F, and IL-21; and play a critical pathogenic role in T cell-mediated autoimmune diseases." (PMID 28458638, 2017). "For future studies using IL-21 to enhance the generation of B10 cells, caution must be taken because IL-21 has also been demonstrated to promote T cell responses, and elevated levels of IL-21 have been implicated in driving autoimmune disease." (PMID 28239367, 2017). "Recently, many studies supported that variant SNPs located within the IL-21 gene have genetic association with susceptibility to different diseases particularly autoimmune diseases." (PMID 29511486, 2017). "These qPCR results are consistent with the observed decrease in IFNγ (T‐bet) and IL‐17 (RORC) secretion levels and are particularly interesting as several investigations have associated IL‐21 to autoimmune diseases." (PMID 26762709, 2016). "Dysregulated Tfh cells, including increased Tfh cell numbers and production of IL-21, have been implicated in a number of autoimmune diseases." (PMID 31557986, 2016). "It will be important to determine if the variants mapping to the IL2-IL21 region that influence susceptibility to type 1 diabetes and other autoimmune diseases directly influence IL-2 or IL-21 production in a cell-intrinsic manner." (PMID 25652388, 2015). "Increased serum IL-21 concentrations related to a specific genetic risk profile have been shown to correlate with the incidence of autoimmune disease after alemtuzumab." (PMID 26204829, 2015). "Increasing evidence is supporting the role of IL-21 as a susceptibility gene contributing to multiple autoimmune diseases, including GD." (PMID 24944624, 2014). "Collectively, there is convincing evidence that IL-21 – most likely produced by Tfh cells – plays a pathological role in the initiation, development, and/or progression of several human autoimmune diseases caused by the production of autoantibodies." (PMID 24600453, 2014). "In recent years, the associations between the IL-21 gene or IL-21R gene polymorphisms and autoimmune diseases have been gradually reported." (PMID 23889847, 2013). "Dysregulation of Tfh cell function, or expression of Tfh cell-associated molecules such as ICOS or IL-21, contributes to the pathogenesis of certain autoimmune diseases in animal models." (PMID 24069044, 2013). "IL-2 promotes development of regulatory T cells and confers protection from autoimmune disease whereas IL-21 promotes differentiation of Th17 cells and is implicated in the development of several autoimmune diseases." (PMID 23676143, 2013). "In this study we selected variants that were most significantly associated with autoimmune disease susceptibility and are the first, to our knowledge to investigate variants within the IL-21 gene region for prostate cancer risk." (PMID 20184734, 2010). "It has been demonstrated recently that IL-21 plays a pivotal role in either initial or acquired immunity and is closely associated with several autoimmune diseases, such as multiple sclerosis and inflammatory bowl disease." (PMID 20057909, 2009). "The pro-inflammatory functions of IL-21 are also associated with many autoimmune disease models, including experimental autoimmune encephalomayelitis, adjuvant-induced arthritis and experimental colitis." (PMID 20057909, 2009).
autoimmune disease (continued). "These include a region on chromosome 4q27 that contains genes for interleukin 2 and interleukin 21 that has been recently implicated in other autoimmune diseases, and seven additional regions that include chromosome 13q13 and 15q21." (PMID 18369459, 2008). "It will be interesting to learn whether human cases of autoimmune diseases that map to the IL21/IL2 locus carry specific variants in the region syntenic to the 39 kb deletion." (PMID 39746095, 2025). "Our results suggest that distant variants upstream of IL21 could also be important for human autoimmune diseases that have been found to be associated with the IL21/IL2 chromosome region." (PMID 39746095, 2025). "Additionally, IL‐21, a cytokine primarily produced by Th17 cells, has been implicated in the development of autoimmune diseases." (PMID 37506162, 2023). "Studies have shown that irAEs caused by ICIs have a pathogenesis similar to that of autoimmune disorders, and hyperreactivity of Th17 cells and proinflammatory cytokines such as IL-17A, IL-21 and IL-22 have prominent roles in the pathogenesis of many autoimmune diseases." (PMID 36793048, 2023). "However, IL-21 is also implicated in multiple autoimmune diseases including systemic lupus erythematosus, rheumatoid arthritis, multiple sclerosis, and inflammatory bowel disease." (PMID 37339051, 2023). "IL-21 can also be produced by Th17 and has various effects, ranging from Tfh and Th17 cell development, helper T-cell subset balance, production of B cells and immunoglobulins, and plasma cell differentiation, and is also associated with autoimmune diseases." (PMID 35265152, 2022). "The blockade of JAK/STAT pathway might serve as the strategy to treat autoimmune diseases associated with IL-4 and IL-21 upregulation." (PMID 35911775, 2022). "The second approach could be blockade of the IL-21 pathway proven to affect the production of pathogenic immunoglobulins in animal models of autoimmune diseases." (PMID 27602031, 2016). "Genome-wide association studies have identified the locus encoding Il21 and Il2 as a risk factor for autoimmune diseases such as systemic lupus erythematosus (SLE), type 1 diabetes, inflammatory bowel disease, coeliac disease, psoriasis and psoriatic arthritis." (PMID 31557986, 2016). "Besides elevated IL-21, reduced IL-7 levels correlated with an increased risk of autoimmune disease after alemtuzumab." (PMID 26204829, 2015). "Independent confirmation that IL-21/IL-21R may be involved in the development of autoimmune diseases came from genome-wide association studies." (PMID 24600453, 2014). "IL-21 is also implicated in the development of autoimmune disease and has antitumor activity." (PMID 24069044, 2013). "IL-21 has been implicated in autoimmunity disease via the IL-21R pathway." (PMID 23176102, 2012). "Moreover, IL-21 is associated with the induction of Th 17 cells, B cell differentiation, antibody production and inhibition of Treg function potentially promoting secondary autoimmune disorders." (PMID 26966029, 2016). "Since previous observations suggest that IL-21 and IL-21R may be associated with immunoglobulin production, autoantibody production, and B lymphocyte hyperactivity, IL-21 may be involved in the pathogenesis of autoimmune diseases." (PMID 27386263, 2016). "Thus, IL-21+ T-cells might contribute to the generation of pathogenic T-cells in this autoimmune disease." (PMID 21959034, 2011). "Tph cells have been shown to mediate B cell help through production of IL-21, and are believed to participate in many autoimmune diseases, including rheumatoid arthritis (RA), Sjögren’s syndrome (SS), and systemic lupus erythematosus (SLE)." (PMID 40519906, 2025). "By understanding these interactions, researchers have identified potential therapeutic targets, with the IL-21 blockade emerging as a promising strategy in managing autoimmune disease symptoms and slowing progression." (PMID 40283219, 2025).
autoimmune disease (continued). "Th17-related cytokines—interleukin (IL)-17, IL-21, and IL-22—play distinct and complementary roles in the pathogenesis of autoimmune diseases." (PMID 41035651, 2025). "As a member of the type I cytokine family, IL-21 profoundly affects immune cell fate and is involved in immune regulation in diseases such as autoimmune disorders, allergies, transplant rejection, and cancer." (PMID 40376002, 2025). "Such multifunctional IL-21+IFN-γ+ Tfh CD4+ cells have previously been described as mediators of immune response in spontaneous autoimmune diseases (e.g., lupus and peripheral neuropathy) and viral infections." (PMID 40626363, 2025). "Beyond psoriasis, IL-21’s contribution to autoimmune diseases further highlights its potential as a therapeutic target​." (PMID 40161116, 2025). "TPh cells have been shown to assist B cells in inflamed tissues in autoimmune diseases, act as major IL-21 producers and contribute to the pathogenesis of a wide range of autoimmune diseases." (PMID 40824218, 2025). "Our genome-wide pleiotropy study further identified a gene cluster on the 4q27 chromosome region, encompassing KIAA1109, IL2, IL21, and ADAD1 genes, reporting a strong literature support for association with most autoimmune diseases and AD." (PMID 41009683, 2025). "For example, IL-21's interaction with B cells enhances the production of autoantibodies, which are key markers of autoimmune diseases." (PMID 40161116, 2025). "Here, we demonstrate that IL-21, a proinflammatory cytokine elevated in autoimmune disorders, chronic viral infections, and Alzheimer’s disease, activates microglia and promotes lipid accumulation within these cells." (PMID 40301833, 2025). "A major contribution of Tfh cells to autoimmune diseases is through their production of cytokines, particularly IL-21, which supports the proliferation and differentiation of autoreactive B cells." (PMID 40283219, 2025). "Clearly, enhanced expression of IL21 can be instrumental in the etiology of these autoimmune diseases." (PMID 39746095, 2025). "Overexpression of IL-21 is observed in tissues and sera of human patients with autoimmune diseases such as systematic lupus erythematosus (SLE), rheumatoid arthritis (RA), type 1 diabetes mellitus (DM), and primary Sjögren syndrome (SS)." (PMID 39746095, 2025). "IL36A and IL21 actively participate in autoimmune disease, activating downstream pro-inflammatory pathways, thus promoting inflammatory responses." (PMID 39762453, 2025). "Tfh cells have been reported as a major source of IL-21 in various inflammatory and autoimmune diseases." (PMID 39925810, 2025). "Given the critical role of IL-21 in Tfh-cell function, blocking IL-21 signaling is a promising approach for reducing autoantibody production in autoimmune diseases." (PMID 40283219, 2025). "Multiple research projects indicate the essential roles of IL‐6, IL‐10, IL‐21, and IL‐17 in the pathogenesis of autoimmune diseases." (PMID 36271684, 2024). "IL-21 contributes to the pathogenesis of autoimmune disorders and has been suggested as a therapeutic target for SLE, TID, rheumatoid arthritis, etc." (PMID 39346912, 2024). "The IL‐21 cytokine and ROS overproduction have a role in autoimmune disorders, such as RA progression and development." (PMID 39056553, 2024). "Th17-derived proinflammatory cytokines (IL-17A, IL-17F, IL-21, IL-22, and IL-26) have a critical role in the pathogenesis of several autoimmune diseases such as psoriasis, multiple sclerosis, rheumatoid arthritis, and inflammatory bowel disease." (PMID 37495626, 2023). "Considering the possible role of inflammatory processes in AN, changes in IL-21 levels, demonstrated in various types of autoimmune diseases, can also play a significant role." (PMID 37432371, 2023). "Our results add new insight into the mechanisms of IL-21-mediated pathogenesis of autoimmune diseases and the development and maintenance of Vγ4+γδT17 cells." (PMID 37662923, 2023).